MUC2 (mucin 2, oligomeric mucus/gel-forming)
Diseases named in the same sentence as MUC2 in open-access papers (continued):
Sharing a sentence is not in itself a finding about the gene and the disease.
mucinous adenocarcinoma (continued). "In mucinous adenocarcinoma, the expression of MUC2 is significantly elevated, possibly due to the maintenance of Atoh1 expression by the SCF/c-kit signaling pathway, which leads to mucinous colorectal adenocarcinoma (MCA)." (PMID 32695780, 2020). "We found that signet ring cell carcinoma and mucinous adenocarcinoma have the highest total score of MUC2, while KLF4 score is variable in these tumors due to different localization of KLF4 in the tissues." (PMID 27277677, 2016). "In nude mice, LS174T grew as a mucinous adenocarcinoma microscopically resembling the original tumor with the expression of the intestinal goblet cell-specific secreted mucins, of which MUC2 is most prominently expressed." (PMID 26436698, 2015). "Mucinous carcinoma has high MUC2 expression compared to other adenocarcinomas in the pancreas, bile duct, ovary, breast and colorectum." (PMID 25551773, 2014). "MUC2 and also, other intestinal secretory mucins, have been found in other mucinous adenocarcinomas, such as those of the pancreas, salivary glands, biliary tract, the ampulla of Vater, the stomach, endometrium, lung, and ovary, among others." (PMID 25299496, 2014). "MUC2 expression was related to tumor location (high for anal side, p = 0.034), negative lymphatic invasion (p = 0.041) and histological type (high for mucinous carcinoma, p = 0.005)." (PMID 24722639, 2014). "Some mucinous adenocarcinomas have shown expression of intestinal differentiation markers such as MUC-2." (PMID 25299496, 2014). "Mucin 2 (MUC2) is the major secreted mucin of the large intestine and is expressed by adenomas and mucinous carcinomas." (PMID 25322805, 2014). "When analyzing different histological GC groups, we found the phenotype of PGC-/MUC1-/MUC2+ all distributed in the group of mucinous adenocarcinoma or signet ring cell carcinoma (MA or SRCC, 100%, 6/6)." (PMID 23937908, 2013). "Expression of MUC2 is reduced in colorectal adenocarcinoma, although expression is observed in mucinous carcinomas." (PMID 18000536, 2007). "Patients with mucinous carcinomas generally exhibit elevated production of MUC2 in the GI tract; this may be correlated with low MUC2 gene methylation." (PMID 35933341, 2022). "Furthermore, MUC2 is enriched in mucinous adenocarcinoma and can be lost during the carcinogenic process in conventional adenocarcinoma." (PMID 31904088, 2020). "The role of MUC2 in mucinous carcinoma suggests that production of this type of mucin may act as a barrier to cancerous extension, resulting in the indolent nature of many tumors." (PMID 25551773, 2014). "Colliquative and/or dirty necrosis are predominantly found in MUC1-positive adenocarcinomas of the pancreas and colorectum, whereas the absence of necrotic phenomena is characteristically found in MUC2-positive mucinous adenocarcinomas of the gastrointestinal tract." (PMID 25202341, 2014). "Mucinous carcinoma of breast predominantly expresses the secretary mucins, MUC2 and MUC6." (PMID 20550696, 2010). "The investigation stemmed from the observation of an inverse correlation between MUC2 expression and the immune constant of rejection (ICR) score in mucinous adenocarcinomas compared to other histological types." (PMID 39926604, 2024). "Our results indicate that mucinous adenocarcinoma cancer cells have goblet cell-like properties, and express high levels of goblet cell markers (REG4, SPINK4, FCGBP and MUC2) compared to classical adenocarcinoma cancer cells." (PMID 36690709, 2023). "The mucinous adenocarcinoma characterized genes, such as MUC1 and MUC2, were significantly enriched in cancer cells from CRC2." (PMID 36038820, 2022). "Among these mucins, Mucin-2 (MUC-2) is the major secreted form, shown to be expressed by intestinal adenomas and especially by mucinous carcinomas." (PMID 34638991, 2021).
mucinous adenocarcinoma (continued). "They supposed two progression pathways of IPNB to tubular adenocarcinoma and mucinous carcinoma, featuring the phenotypes of MUC1+/MUC2+ and MUC1−/MUC2+, respectively, which are analogous to that of IPMN of the pancreas." (PMID 24949206, 2014). "Choi and his colleagues found mucinous adenocarcinoma always showed MUC1- and MUC2+ in a study of 133 MA cases, which was consistent with the result of our study." (PMID 23937908, 2013). "MUC2 importance stems from the fact that it not expressed by normal pancreatic tissue, but it can be found in IPMNs of the intestinal type and in colloid carcinomas." (PMID 39594780, 2024). "MUC2 was negative in all primary lung cancers, but positive only in less than half of pulmonary metastases from mucinous adenocarcinomas from other organs." (PMID 37349623, 2024). "In invasive carcinomas arising from IPMNs, colloid carcinomas are characterized by MUC2, while lacking MUC1 expression." (PMID 39594780, 2024). "Similar results were found for MUC5AC in 10 mucinous adenocarcinomas (mBAC) (100%), but not for MUC2 (0%) in another study." (PMID 36367122, 2023). "This pattern is not surprising, as normal colonic tissue expresses MUC2; therefore, these polyps have not yet lost their expression the way some non-mucinous adenocarcinomas have." (PMID 36900282, 2023). "On the other hand, mucinous adenocarcinoma component was positive for MUC2, and negative for MUC5AC and CD10, indicating the intestinal type." (PMID 33452648, 2021). "First, MUC2 is mainly expressed in normal colon epithelial cells, and there is a difference in MUC2 expression between mucinous carcinomas and nonmucinous carcinomas, suggesting the diverse molecular mechanisms involved in these processes." (PMID 32695780, 2020). "Elevated MUC2 expression was associated with CRC in the colon, shallower lesions, negative lymph node metastasis, early stage of tumor, mucinous carcinoma, and larger tumor size." (PMID 31933627, 2019). "Earlier, a study showed that in a BC patient cohort, MUC2 was expressed in all mucinous carcinomas, 11.2% of invasive ductal carcinomas, and none of the invasive lobular and medullary carcinomas, whereas MUC1 was expressed in invasive BC, but not in medullary carcinomas." (PMID 36980526, 2023). "Notably, mucinous adenocarcinomas are characterized by MUC2 overexpression and the absence of dirty necrosis." (PMID 25202341, 2014). "Interestingly, goblet-specific mucin 2 (MUC2) was absent in most PDOs but massively produced in the organoid derived from the mucinous adenocarcinoma of patient 13 (third and fourth rows), consistent with the histopathological features of the clinical specimen." (PMID 33879786, 2021). "In a study comparing 7 mucinous adenocarcinomas (previously known as mucinous bronchioloalveolar carcinoma (mBAC)) and 27 non-mucinous BAC, higher levels of MUC2, MUC5AC, and MUC6 expression were found in mucinous BAC." (PMID 36367122, 2023).
adenoma (29 papers, 2005 to 2026). A neoplasm arising from the epithelium. "A previous study indicated that loss of MUC2 expression was observed during the adenoma-carcinoma sequence." (PMID 28725043, 2017). "Thus, the loss of MUC2, which is likely mediated in part by the Wnt/β-catenin pathway via two disparate mechanisms, typically occurs during the polyp-adenoma-carcinoma sequence and contributes to CRC progression." (PMID 27551331, 2016). "PDK expression was also increased in human hyperplastic polyps and adenomas, whilst MUC2 expression was reduced in adenomas and carcinomas compared to normal mucosa." (PMID 42236792, 2026). "For example, the number of goblet cells and mucin-positive cells in the colon was reduced in sodium/hydrogen exchanger 8 KO mice, along with mucosal pH, MUC2 expression, as well as downregulated adenoma expression." (PMID 38397074, 2024). "It is a critically important protective effect in the colon and has been demonstrated by utilizing MUC2-null mice that developed spontaneous colitis and adenomas leading to invasive adenocarcinoma." (PMID 32168759, 2020). "We found that cells within the adenomas of ApcMin/+ mice expressed less Retnlb and Muc2 mRNA than cells in normal adjacent tissue." (PMID 28710436, 2017). "For the adenoma-specific mutations, we identified two genes (NPIPB5 and MUC2) with a substantial enrichment (P = 0.018 and 0.09, respectively)." (PMID 26336987, 2015). "On the other hand, more differentiated gastric tumors tend to express MUC2 in both tumor lesions and background mucosa (adenoma>tub1> tub2)." (PMID 23451082, 2013). "Adenoma cultures contained scattered goblet-like cells judged by MUC2 staining, but appeared to lack CHGA+ cells consistent with previous observations and stainings on the corresponding primary tumor material." (PMID 24144042, 2013). "Among the most down-regulated genes, we found Slc26a3 (solute carrier family 26, member 3, also known as down-regulated in adenoma (Dra)), Mptx (mucosal pentraxin), Retnla (resistin like-α), Muc2 (mucin 2)." (PMID 20459814, 2010). "Importantly, mucins in Smad4Δ/Δ adenomas were among the DEGs with Muc4, Muc20, Muc2 being upregulated and Muc6 being downregulated (padj p < 0.05)." (PMID 40348815, 2025). "Importantly, also treatment of human epithelial organoid cultures derived either from normal, adenoma or adenocarcinoma tissues with DBZ, caused a clear increase in goblet cells and a significant induction of MUC2 mRNA level." (PMID 24144042, 2013). "In comparison to hyperplastic polyps, traditional adenomas showed lower levels of MUC2 expression." (PMID 20929551, 2010). "Upregulated in adenoma samples was a cluster of the proteins FCGBP, SGSH, MUC2, and PRSS8 when compared to adenomas, of which the latter two are known to play an important role in maintaining a healthy colonic epithelium." (PMID 36369736, 2022). "Expression scores of CTSE, MUC5AC, and MUC2 (from 1 to 4 respectively) in gastric tumors cells (cancer or adenoma) and adjacent normal cells (non-tumorous epithelial cells of background mucosa)." (PMID 23451082, 2013).
Obesity (24 papers, 2016 to 2026). Accumulation of substantial excess body fat. "High saturated fatty acids diets present risk factors for obesity and associated metabolic disorders by affecting Muc2 production." (PMID 39004626, 2024). "We also found that obesity affects the intestinal barrier integrity by downregulating the expression levels of MUC2, an important factor that promotes barrier integrity by producing mucus and by protecting the intestine against pathogens." (PMID 39305371, 2025). "Obesity-induced misfolding of Muc2 (as determined by Muc2 precursor staining) was reduced following treatment with the higher IL-22 dose." (PMID 27350069, 2016). "Obesity can lead to dysbiosis of the gut microbiota via disruption of the intestinal barrier, including tight junction proteins (claudins and ZO-1), the mucus layer (Muc2), and IgA secretion." (PMID 38247213, 2024). "Gut dysbiosis is also a well-recognised factor contributing to the pathophysiology of obesity, implying that MUC2 expression could contribute to IPF and BMI." (PMID 39103522, 2024). "In addition, the gene expression of a secreted mucin with a physical barrier function, MUC2 (Muc2), also decreased with obesity." (PMID 36911680, 2023). "Specifically, oral A. muciniphila administration as a prebiotic treatment for diet-induced obesity mice not only increased Muc2 protein production to restore mucus layer thickness but also prevented the intestinal barrier from injury via decreasing high fat-induced endotoxemia." (PMID 32153527, 2020). "However, whether and how glycosylation of Muc2 directly protects against obesity and metabolic syndrome remain to be investigated." (PMID 39004626, 2024). "In enteroids from patients with obesity, treatment with the HDAC inhibitor SAHA induced an increase (p < 0.05) in ALPI (3.9-fold) mRNA expression and a decrease (p < 0.01) in MUC2 (0.2-fold) and CHGA (0.2-fold) mRNA expression." (PMID 38125020, 2023). "In enteroids from patients with obesity, SCFAs (1 mM) increased (p < 0.05) ALPI mRNA expression 2.9-fold, but decreased (p < 0.01) MUC2 (0.4-fold) and CHGA (0.3-fold) mRNA expression." (PMID 38125020, 2023). "Importantly, the ACM obtained from patients with obesity downregulated the expression levels of TJP1 and MUC2, suggesting a crosstalk between adipocytes and intestinal cells in which the pro-inflammatory profile of adipocytes may impair the integrity of intestinal barrier." (PMID 38315242, 2024).
breast carcinoma (23 papers, 2012 to 2024). "We observed the MUC2 T1750N variant in breast cancer [DOID:1612], liver cancer [DOID:3571], thyroid cancer [DOID:1781], ovarian cancer [DOID:2394], prostate cancer [DOID:10283], brain cancer [DOID:1319], and rectum cancer [DOID:1993]." (PMID 29531238, 2018). "MUC2 plays an important role in mediating the proliferation, apoptosis and metastasis of breast cancer." (PMID 35205681, 2022). "Of the five biomarkers, three genes (EDN2, WT1, and MUC2) were upregulated in the breast cancer samples while CLEC3B and SV2C were decreased." (PMID 34513664, 2021). "We screened out five protein coding genes (EDN2, CLEC3B, SV2C, WT1, and MUC2) significantly corresponding to the overall survival time of patients with breast cancer in the training group." (PMID 34513664, 2021). "Functioned as an oncogene, MUC2 was highly expressed in mucin secreting breast cancers and played a pivotal role in regulating cell proliferation, metastasis, and apoptosis." (PMID 34513664, 2021). "In our study, we aimed to evaluate serum MUC2 levels in patients with breast cancer and age and sex-matched healthy controls." (PMID 30682816, 2019). "There are only a few studies that evaluated the clinical implication of MUC2 expression in breast cancer tissue." (PMID 30682816, 2019). "This study was conducted to investigate the serum levels of membrane-bound mucin 2 (MUC2) in breast cancer (BC) patients and the relationship with tumour progression and known prognostic parameters." (PMID 30682816, 2019). "Moreover, we computed SSES metrics for two genes: CAMKV and MUC2, which have been previously reported to play an important role in mediating proliferation, apoptosis and metastasis of breast cancer cells." (PMID 39003292, 2024). "MUC2 is a protein that is highly expressed in mucin secreted breast cancers." (PMID 35205681, 2022). "In some preclinical studies, MUC2 expression was evaluated in breast cancer tissue." (PMID 30682816, 2019). "MUC2 may be important to guide treatment and predict outcomes in breast cancer patients." (PMID 37337182, 2023). "For diagnostics purposes, antibodies associated with breast carcinoma include estrogen receptor (ER), progesterone receptor (PR), gross cystic fluid protein (GCDFP), HER-2/neu, cytokeratins (CK5/6, CK7, CK20), and the mucin glycoprotein antibodies, namely, MUC2, MUC3, MUC5AC, MUC6, and DAS-1." (PMID 24066246, 2013). "Genes extracted from the gene expression omic dataset that play key roles in the development of breast cancer are CDCA5, IL17RB, MUC2, NOD2, and NXPH4." (PMID 35205681, 2022). "MUC2 is expressed in pre-malignant breast lesions like ductal carcinoma in situ (DCIS), and is upregulated in lobular carcinoma in situ (LCIS)." (PMID 30682816, 2019). "We have described clinicopathological characteristics of patients with breast cancer containing SRCs in relation to the expression levels of MUC1, MUC2, MUC4, MUC5AC, and MUC6." (PMID 27846863, 2016). "In breast cancer, most tumors express MUC1 and MUC3, and the expression of MUC2, MUC4, MUC5AC, and MUC6 is variable or limited." (PMID 27846863, 2016). "Among the four polymerizing mucins MUC2, MUC5B, MUC5AC, and MUC6 whose altered expression has been reported in breast cancer tissues, the role of MUC5B is poorly documented." (PMID 23056409, 2012). "MUC2 overexpression has repeatedly been demonstrated as a poor prognostic factor for non-digestive system cancers, such as breast cancer, bladder cancer and ovarian cancer, in previous studies." (PMID 24324582, 2013). "However, to the best of our knowledge, the clinical significance of serum MUC2 levels in breast cancer has not been previously examined." (PMID 30682816, 2019).
inflammatory bowel disease (23 papers, 2013 to 2025). A spectrum of small and large bowel inflammatory diseases of unknown etiology. "Endoplasmic reticulum (ER) stress compromises the secretion of MUC2 from goblet cells and has been linked with inflammatory bowel disease (IBD)." (PMID 33985416, 2021). "Altered MUC2 secretion has been implicated in animal NEC models as well as in inflammatory bowel disease." (PMID 32753526, 2020). "An increase in acetate concentration in the IDF and SDF groups might be the partial reason for the increase of MUC2 mRNA level, since acetate has been shown to prevent inflammatory bowel diseases by inducing mucin secretion in mucin-deficient mice." (PMID 31950054, 2019). "The full sequences of these mucins will now allow such studies, which could be of importance for inflammatory bowel diseases for MUC2 and gastric ulcer diseases for MUC6 where deficient mucus protection is assumed to play an important role." (PMID 30504806, 2018). "Targeting the expression and functionality of tight junction proteins, along with MUC2, represents a promising new therapeutic strategy to enhance intestinal barrier integrity in inflammatory bowel disease (IBD)." (PMID 39830908, 2025). "Previous work showed that IL-33, a cytokine upregulated in inflammatory bowel disease and helminth infections like N. brasiliensis, induces intestinal goblet cells and Muc2 expression in mice through IL-13 production by innate lymphoid cells." (PMID 38721267, 2024). "Meanwhile, the MUC2 is the structural component of the intestinal epithelium mucus layer and its expression is lowered in inflammatory bowel disease." (PMID 35769317, 2022). "MUC2 could be similarly analyzed from inflammatory bowel disease stools, which displayed an altered glycomic profile and differential growth and SCFA production by B. theta versus healthy samples." (PMID 38272223, 2024). "FCGBP function as a mucin-like glycoprotein cooperated with MUC2, both of which were crucially essential part of mucus layers of the colon barrier, and might play a role in cell protection and inflammatory bowel disease." (PMID 31956350, 2020). "In patients with inflammatory bowel disease (IBD), goblet cell depletion is present in the colon in inflamed lesions compared to healthy lesions, and altered mucus layer thickness with reduced MUC2 has also been found." (PMID 35682612, 2022). "Our patient with UC had significant reduction of the MUC2, MUC3 expression, and mucins production in comparing with CD patients that can be additional differential criteria for these two inflammatory bowel diseases." (PMID 23737764, 2013). "The fact that both treatments led to significant improvements in MUC2 and tight junction protein expressions points to their potential utility in clinical settings, particularly for conditions characterized by barrier dysfunction, such as inflammatory bowel diseases (IBD)." (PMID 39840100, 2024).